ACE (angiotensin I converting enzyme)
Diseases named in the same sentence as ACE in open-access papers (continued):
Sharing a sentence is not in itself a finding about the gene and the disease.
dyslipidemia (197 papers, 2009 to 2026). "Posteriorly, their ability to inhibit the enzymatic activities associated with the development of the metabolic syndrome, namely, ACE (antihypertensive), α-glucosidase (antidiabetic), and lipase (antiobesity), was evaluated." (PMID 37238844, 2023). "Afterwards, the same peptides were demonstrated to act as inhibitors of the three enzymes associated with the development of the metabolic syndrome: ACE, α-glucosidase, and lipase." (PMID 37238844, 2023). "Treatment of CKD recommends the control of traditional risk factors such as AH, hyperglycemia, and dyslipidemia with common pharmacological tools, i.e., angiotensin-converting-enzyme (ACE) inhibitors or angiotensin-receptor blocker (ARB) and statins." (PMID 34063052, 2021). "The metabolic syndrome is directly and indirectly associated with damage of the endothelial tissue, major secretory of ET-1 and ACE." (PMID 27894250, 2016). "Besides that, a contribution of D allele of ACE I/D polymorphism to dyslipidemia was also verified by alterations on VLDL-cholesterol (D allele on case group, p = 0.03; DD genotype in all individuals analysis, p = 0.01) and Triglycerides levels (DD genotype in all individuals analysis, p = 0.01)." (PMID 31430320, 2019). "The effect of the elicitation on the activity of the potentially bioavailable fraction of phenolic acids towards the enzymes involved in the pathogenesis of the metabolic syndrome, i.e., ACE, lipase, amylase, and glucosidase, was analyzed as well." (PMID 32630448, 2020). "A group of 23 subjects with untreated metabolic syndrome (MetS) received either aronia extract supplements providing 60 mg ACNs, or ACE-inhibitors." (PMID 31242638, 2019). "The present study was aimed to investigate the association of ACE (rs4646994), FABP2 (rs1799883), MTHFR (rs1801133) and FTO (rs9939609) genes polymorphism in T2DM with dyslipidemia." (PMID 28890888, 2017). "The aim of this study was to determine the associations between the mentioned gene polymorphisms (ACE, MTHFR, FABP2), and T2DM with dyslipidemia." (PMID 28890888, 2017). "The frequency of ACE ID genotype was 65.2% in T2DM cases with dyslipidemia c which is significantly higher in comparison to the Kuwaiti T2DM cases with cardiovascular disease 44.1%." (PMID 28890888, 2017). "We reported previously the antiatherosclerotic activity of ACE using an apoE knockout mouse model, but the present study is the first to demonstrate a pharmaceutical effect of ACE against metabolic syndrome." (PMID 26508977, 2015). "The aim of the study was to analyze the effects of two-month supplementation with Aronia melanocarpa Elliot preparation on the activity of angiotensin I-converting enzyme (ACE) in patients with metabolic syndrome (MS)." (PMID 25050143, 2014). "An ACE inhibitor, quinapril, reduced plasma markers of oxidative stress in metabolic syndrome patients." (PMID 22829804, 2012). "Furthermore, a significant reduction in ACE activity was observed, although still higher compared to a reference group of healthy controls and to another reference group of metabolic syndrome controls receiving ACE-inhibitors’ therapy." (PMID 35807881, 2022). "In conclusion ACE, FABP2, FTO and MTHFR genes were found to be associated with T2DM, and additionally ACE and MTHFR genes might be implicated with the development of dyslipidemia in T2DM cases." (PMID 28890888, 2017). "In an interesting study, DPP-4 inhibition lowered BP during acute administration of the low dose angiotensin-converting enzyme (ACE) inhibitor enalapril, but abolished the acute antihypertensive effects of high dose enalapril in patients with metabolic syndrome." (PMID 25140306, 2014). "Among hypertensive subjects with metabolic syndrome, the presence of ACE polymorphisms, including TT235, MM174, DD, and CC1166 genotypes, could be a risk factor for central obesity and dyslipidemia." (PMID 23800102, 2013).
dyslipidemia (continued). "The compounds include drugs for dyslipidemias such as statins, niacin, fibrates, resins, as well as compounds for other purposes, including angiotensin converting enzyme (ACE) inhibitors, angiotensin receptor blockers, calcium channel blockers, glitazones and anticonvulsants, and alcohol." (PMID 21568932, 2011). "Several drugs are relevant in the management of the metabolic syndrome, but this review will focus on the most commonly used first line drugs recommended in current guidelines, i.e. statins and Angiotensin Converting Enzyme (ACE)-inhibitors/Angiotensin II (ATII) receptor antagonists." (PMID 20331890, 2010). "In these patients, the use of ACE inhibitor and ARB therapy, like in those with the metabolic syndrome, may have an advantage in decreasing the subsequent risk for new-onset diabetes." (PMID 19220522, 2009). "The nanofiber morphology and multivalent presentation of IAVPTGVA and LTFPGSAED peptides as DPP-IV and ACE inhibitors in vitro on Caco-2 human intestinal cells could offer a future targeting strategy for the prevention of metabolic syndrome through their consumption as edible nanonutraceuticals." (PMID 35203539, 2022). "Furthermore, management of dyslipidemia, quitting smoking, exercise, and use of angiotensin-converting enzyme (ACE) inhibitors and angiotensin receptor blockers (ARBs) may improve vascular endothelial function and prevent cardiovascular diseases." (PMID 32958851, 2020). "Additionally, it also seems that ACE and MTHFR genes might be further associated with the development of dyslipidemia in T2DM cases." (PMID 28890888, 2017). "Indeed, ACE inhibitors such as captopril have been demonstrated to improve adipocyte differentiation and exert anti-inflammatory effects in various tissues, suggesting their additional benefits in a complex condition like metabolic syndrome." (PMID 25714093, 2015). "In addition, the RAS may also affect other aspects of the pathogenesis of the metabolic syndrome such as atherosclerosis and insulin resistance, both of which are reported to be reduced by ACE inhibitors." (PMID 26491214, 2015). "ACE and ACE2, that orchestrate together with CD10 the Renin-angiotensin system, play an important role in metabolic syndrome and liver disease development 48,49." (PMID 34131392, 2021). "The highest potential for inhibition of metabolic syndrome was determined in the first fraction obtained from PRO P demonstrating the highest activity, where the IC50 values for ACE, α-amylase, and α-glucosidase were 4.82, 43.56, and 91.38 μg/mL, respectively." (PMID 30841527, 2019). "The effects of ACE inhibitors and ARB on dyslipidemia in the fructose-fed rats observed in this study are similar to those observed in previous studies." (PMID 28700686, 2017). "In DN and metabolic disease, genotype-dependent responses linked to ACE I/D, eNOS, and SOD2 polymorphisms complicate drug selection, while non-vasodilating BBs can exacerbate insulin resistance and dyslipidemia." (PMID 41463309, 2025). "As a result of these findings, sericin peptides can be utilized as novel dietary ingredients that may alleviate some metabolic syndromes via the dual inhibitory properties of DPP-IV and ACE." (PMID 36496739, 2022). "Groups with and without HU differed on dyslipidemia and the presence of cystic diseases, use of ACE inhibitors/angiotensin receptor blockers, and use of diuretics." (PMID 32106421, 2020). "Furthermore, both ACE inhibitors and ARBs protect against HFD-induced weight gain, dyslipidemia, insulin resistance, and glucose intolerance in male rodents." (PMID 31262355, 2019).
dyslipidemia (continued). "In our study, the frequency of ACE II genotype was 35.4% in T2DM without dyslipidemia cases which is significantly higher in comparison with 19.1% in Brazilian and 10.8% in UAE population." (PMID 28890888, 2017). "Significant difference was observed in the frequency of ACE II, ID genotypes when comparing T2DM without dyslipidemia with controls (P<0.001, P=0.007) and T2DM with dyslipidemia (P<0.001, P<0.001)." (PMID 28890888, 2017).
acute kidney injury (182 papers, 2004 to 2026). Sudden and sustained deterioration of the kidney function characterized by decreased glomerular filtration rate, increased serum creatinine or oliguria. "Circulating markers of the RAAS are also associated with renal failure, and both ACE and AngII were elevated in the plasma of male and female DOX-treated rats." (PMID 37373368, 2023). "Administering Angiotensin-converting enzyme (ACE) inhibitors alongside NSAIDs can reduce the antihypertensive effect of this substance class and potentiate the risk of renal failure." (PMID 33661391, 2021). "Further large study on the pediatric Egyptian population from different renal centres will be done for better interpretation for the role of ACE gene polymorphism on the progression of renal failure." (PMID 21859496, 2011). "For instance, ACE inhibitor treatment avoids productivity loss due to renal failure and copayments for the treatment of renal failure, but drug copayments lead to additional costs." (PMID 22022539, 2011). "For the HTN cohort comparing ACE inhibitors versus beta-blockers on the risk of acute kidney injury, effect estimates were impacted by strong confounding by indication with the unadjusted estimate showing a protective effect for individuals initiating ACE inhibitors with a HR of 0.59 (0.52, 0.69)." (PMID 39974094, 2025). "This recommendation is based on adult literature and expert consensus, given the risk of precipitating acute kidney injury ACE inhibitors should be used cautiously in paediatric patients with volume depletion because their elevated renin levels can lead to hypotension." (PMID 41007039, 2025). "Furthermore, combining ACE inhibitors with diuretics and NSAIDs can increase the risk of acute kidney failure." (PMID 38353748, 2024). "In individuals with less severe variants, ACE inhibition might even have the potential to delay renal failure for their lifetime." (PMID 37174733, 2023). "Notably, a combination of ACE inhibitors and ARBs has also been found to be associated with an elevated risk of adverse effects such as acute kidney injury and hyperkalemia." (PMID 35073973, 2022). "In addition, cardiorenal syndrome severely limits the available options of HF medications (ACE-inhibitors/ARBs, MRAs and ARNIs), all of which cumulatively increase risk of acute kidney injury (AKI) and hyperkalaemia in a dose-dependent manner." (PMID 33274396, 2021). "In a large population-based study, the concurrent use of diuretics and ACE inhibitors or ARBs along with NSAIDs was associated with an overall 31% higher risk of acute kidney injury, which is driven by a nearly 2-fold increased risk in the first 30 days of use." (PMID 26656365, 2015). "In addition, there is evidence from the ESCAPE trial that residual urinary protein excretion during angiotensin-converting enzyme (ACE) inhibition is quantitatively associated with renal failure progression." (PMID 18335252, 2008). "The findings clearly establish the association of ACE I/D gene polymorphism with the renal failure." (PMID 17042963, 2006). "However, ACE-inhibition may also cause acute kidney injury in a kidney with diminished arterial flow due to compression caused by a tumor." (PMID 35205701, 2022). "ACE inhibitors, ARBs and diuretics are known for causing an acute kidney injury (AKI) in CKD patients, therefor they were stopped in patients that developed AKI." (PMID 29649334, 2018). "ACE Inhibitors (ACE-I) and Angiotensin-Receptor Antagonists (ARAs) are commonly prescribed but can cause acute kidney injury (AKI) during intercurrent illness." (PMID 24223154, 2013). "The use of RAAS antagonists, particularly ACE inhibitors and ARBs, can reduce renal tissue injury and the incidence of sepsis-induced acute kidney injury." (PMID 41041277, 2025). "The most common ADRs for ACE inhibitors are cough, hypotension, hyperkaliemia, and acute renal failure." (PMID 39457476, 2024).
acute kidney injury (continued). "Sepsis-induced endothelial dysfunction is proposed to cause angiotensin-converting enzyme (ACE) dysfunction and renin–angiotensin–aldosterone system (RAAS) derangement, exacerbating vasodilatory shock and acute kidney injury (AKI)." (PMID 37308975, 2023). "In another study, ACE-inhibition with ramipril was able to prevent cardiac damage in a rat model of cardiac damage following acute kidney injury (AKI)." (PMID 36982497, 2023). "Of note, the reported adverse fetal effects of maternal candesartan treatment, such as renal failure, pulmonary hypoplasia, and skull hypoplasia, are remarkably similar to those reported for maternal treatment with ACE inhibitors." (PMID 36293183, 2022). "COVID patients are typically prescribed ACE inhibitors or ARBs, but these medications should be stopped if they develop co-morbidities, such as hypotension or acute kidney injury, or are in the acute phase of an ischemic stroke." (PMID 35645351, 2022). "An addition of MRAs to the standard ARB treatment or ACE inhibitor has been found to significantly reduce UACR, albuminuria, the decline in eGFR, and the risk of the complex outcome of renal failure or renal-caused death." (PMID 35073973, 2022). "All patients were discharged on oral anticoagulant and beta-blockers, 13 on ACE inhibitors (severe renal failure in one patient), 5 on an aldosterone antagonist, and 12 on furosemide with a mean daily dose of 40 mg (IQR 40)." (PMID 34640519, 2021). "Clinically, hyperkalemia is associated with diseases such as ischemia, renal failure, and HIV; medications such as ACE inhibitors, penicillin, and heparin; and acute injury such as crush injury and burns." (PMID 33660028, 2021). "Acute kidney injury was due to dehydration following severe diarrhea and was corrected by intravascular fluids expansion and discontinuation of diuretics and ACE inhibitors." (PMID 34207314, 2021). "It is possible that our patient progressively developed alcoholic ketoacidosis and acute renal failure from dehydration and excessive drinking in the setting of newly started Angiotensin-converting-enzyme (ACE) inhibitor." (PMID 32699722, 2020). "The factors contributing to acute kidney injury are diuretics, iodinated contrast administration, hemodynamic instability apart from ACE inhibitors, and angiotensin receptor blockers." (PMID 32685221, 2020). "It has been shown that the DD genotype of the gene polymorphism 14094 angiotensin-converting enzyme (ACE) determines the increased activity of the enzyme, which is essential for the pathogenesis of cardiovascular diseases and renal failure." (PMID 27988909, 2017). "ACE, ARA, NSAID, diuretics, and iodinated CM have the potential to cause LA indirectly by acute renal failure; ARV drugs by direct action on mitochondrial activity." (PMID 27034959, 2016). "Angiotensin-converting enzyme (ACE) inhibition has been shown to delay renal failure and prolong life expectancy in males with XLAS and in individuals with autosomal recessive AS." (PMID 26249550, 2015). "Here the cat temporarily responded to an ACE inhibitor and steroid therapy but died due to the progression of renal failure." (PMID 26445234, 2015). "Retrospective observational data show that ACE-inhibitor therapy delays renal failure and improves life expectancy in Alport patients with proteinuria." (PMID 22811928, 2012). "Moreover, at present, the perioperative ACE inhibitors and ARBs use in hypovolemia and pre-existing renal insufficiency patients is debatable owing to the risks, including acute kidney injury (AKI) and hypotension." (PMID 40125184, 2025). "BM-MSCs-eRLX + GFP produced greater renoprotective and therapeutic efficacy over that of BM-MSCs-eGFP or ACE inhibition, and may represent a novel and safe treatment option for acute kidney injury and hypertensive CKD." (PMID 39443975, 2024).
acute kidney injury (continued). "Furthermore, reduced ACE and ACE2 function are associated with acute kidney injury (AKI) and mortality, respectively, in critically ill patients." (PMID 34391450, 2021). "Regarding drug–drug interactions, 2.33% of analyzed prescriptions contained the association of an ACE inhibitor and an ARB for patients with renal failure (identified based on the diagnostic code), followed by the association of AVK and NSAIDs in 0.43% of cases." (PMID 34280980, 2021). "There were only two reported incidences of acute kidney injury, both occurring with ACE inhibitors." (PMID 32216794, 2020). "The ACE inhibitors and ARBs were stopped in these patients due to acute kidney injury." (PMID 32685221, 2020). "Dual RAAS blockade therapies combining a direct renin inhibitor aliskiren with an angiotensin-converting enzyme (ACE) inhibitor or an ARB have been associated with increased risk of hypotension, hyperkalemia, and changes in renal function (including acute renal failure)." (PMID 30848243, 2019). "However, combining ACE inhibitors with ARBs offers no added benefits and increases the risk of hyperkalemia, hypotension, and renal failure." (PMID 39941397, 2025). "ACE- angiotensin-converting enzyme, AKI- acute kidney injury, IL- interleukin, TLR- toll-like receptors, TNF- tumor necrosis factor, GM-CSF- granulocyte/monocyte-colony stimulating factor, G-CSF- granulocyte-colony stimulating factor." (PMID 32963910, 2020). "Interestingly, cases of renal failure with SGLT-2 inhibitors were four times more likely to report concomitant use of angiotensin converting enzyme (ACE) inhibitors, angiotensin II receptor blockers (ARBs), and diuretics, compared to cases with SGLT-2 inhibitors reporting other adverse events." (PMID 31275667, 2019). "In addition, in T2DM patients with CKD, the use of finerenone (added to angiotensin-converting enzyme inhibitors (ACE-i) or angiotensin type II receptor blockers (ARBs), when residual albuminuria is present) is recommended to reduce the risk of cardiovascular disease and renal failure." (PMID 40004579, 2025). "This ACE inhibitory property of the phenolic-rich extracts from the Allium sativum clearly showed that the extracts could inhibit ACE in vitro, and this could explain the possible mechanism for their use in the management/treatment of renal failure in folklore." (PMID 23847460, 2013). "Physicians should be aware of the risk of acute kidney injury with NaP preparations and should not use it in older patients, in those with preexisting renal insufficiency, and in patients on medications that can affect volume status or renal function (diuretics, ACE inhibitors, and ARBs)." (PMID 21492418, 2011). "Among the patients older than 70 years without a diagnosis of preoperative renal failure, therapy with angiotensin-converting enzyme (ACE) inhibitors, CPB duration, male gender and preoperative haematocrit <36% were significant risk factors for AKI." (PMID 33113315, 2021). "Both ARB and ACE inhibitors suppress RAS and slow the progression of DN, but increase blood potassium levels in diabetic patients with renal failure, which may be exacerbated by diabetic acidosis." (PMID 34289001, 2021). "Regarding the misuse of medicines, 2.33% of analyzed prescriptions contained an angiotensin-converting enzyme (ACE) inhibitor and an angiotensin II receptor blocker (ARB) for patients with renal failure in addition to vitamin K antagonists (AVKs) and NSAIDs in 0.43% of cases." (PMID 34280980, 2021). "For example, using AT1 receptor blockers and ACE inhibitors in elderly patients with renal impairment is not recommended, since they can worsen renal failure." (PMID 24119466, 2013). "Hence, it was not surprising not to see a significant reduction in the omission of ACE inhibitor in patients with DM and renal failure, although it was a common PPO." (PMID 32695426, 2020).